EZH2 (enhancer of zeste 2 polycomb repressive complex 2 subunit)
Diseases named in the same sentence as EZH2 in open-access papers (continued):
Sharing a sentence is not in itself a finding about the gene and the disease.
tumor (continued). "Our investigations on murine and human BLBC cell lines corroborated the occurrence of EZH2-specific tumor-suppressive activity and described thereby a new molecular mechanism by which PRC2/EZH2 can exert its repressive function on the EMT transcriptional program." (PMID 34845197, 2021). "The EZH2 inhibitor did not dramatically alter intratumoral MDSCs, while significantly reprogrammed TAMs infiltrates, decreasing tumor-promoting M2 TAMs and increasing tumor-inhibiting M1 TAMs." (PMID 34830196, 2021). "Similarly, EZH2 and DOT1L are other histone methyltransferases whose inhibition leads to MYC downregulation, resulting in tumor growth suppression through slightly different mechanisms." (PMID 35582389, 2021). "We also observed copy number gains in EZH2 (chr7:148,504,464–148,581,441), PTEN (with LOH, chr10:89,622,870–89,731,687), and EED (chr11:85,955,806–85,989,785) in both the cell line and tumor Like NF1, the tumor suppressor CDKN2A is frequently mutated in NF1-associated MPNSTs." (PMID 33707600, 2021). "This negative-feedback loop leads to the upregulation of OGT and EZH2 in metastatic CRC eventually resulting in tumor development." (PMID 32448308, 2020). "In these ceRNA triplets, miR-484, miR-181a-5p, miR-423-5p and let-7b-5p were identified as miRNA biomarkers with excellent distinguishing ability between normal and tumor tissues, and ANKRD36, PCGF2, EZH2 and ATP6V1F were closely related to the prognosis of corresponding cancer." (PMID 33194594, 2020). "In addition to the indicated tumour suppressor genes, it has been determined that HOTAIR can mediate interaction of EZH2 with the specific region of PTEN." (PMID 32245498, 2020). "Interestingly, in our cohort, the expression of FAK, EZH2, H3K27me3, and PCNA inversely correlated with tumor size: Higher expression of these proteins was found in smaller cirrhotic HCCs." (PMID 32806748, 2020). "For example, through a methyltransferase-independent mechanism, EZH2 induces transcriptional activation of RelB, a noncanonical NF-kB factor, to sustain tumor phenotypes in triple-negative breast cancer (TNBC)." (PMID 33327550, 2020). "Consequently, the highly active EZH2/Lat1 positive feedback loop promotes the generation of SAM, which enhances the histone methyltransferase activity of EZH2 and accelerates tumor progression." (PMID 32448308, 2020). "In our experiment, we also found that the use of EPZ-6438 to inhibit EZH2 activity in CRC does not inhibit tumor growth." (PMID 31065671, 2020). "The high expression of EZH2 indicates a poor prognosis of NSCLC, which may be related to tumor stage or cancer type." (PMID 33299862, 2020). "Moreover, AMPK is able to phosphorylate enhancer of zeste 2 polycomb repressive complex 2 subunit (EZH2) and thereby disrupts the polycomb repressive complex 2 (PRC2), which relieves the epigenetic silence of tumor suppressors in cancers." (PMID 32807225, 2020). "Likewise, destabilizing EZH2 protein by HSP90 inhibitor, AUY922, reduces GvHD and tumor burden, leading to significantly improved overall survival in a mouse model of allo-HSCT." (PMID 32560120, 2020). "A xenograft tumor model in nude mice was established to probe further how LINC00152 could promote EMT and resistance of EC cells to L-OHP treatment via the EZH2/ZEB1 axis." (PMID 33292221, 2020). "IHC staining showed decreased expression of EZH2, CCL5, and MMP2 in tumor tissues." (PMID 31855281, 2020). "EZH2, an important member of PRC2, could mediate H3K27me3 and exert oncogenic functions through repressing tumour suppressors." (PMID 31924214, 2020). "A recent study demonstrated that 3-deazaneplanocin A, an EZH2 inhibitor, was shown to suppress NK tumor cell growth and increase the apoptosis of these cells and treatment with a JAK3 inhibitor such as tofacitinib enhanced H3K27me3 in ENKTL tumor cell lines." (PMID 32098335, 2020).
tumor (continued). "Moreover, the tumor suppressor locus Ink4a/Arf, E-cadherin, FOXC1, and components of DNA damage repair pathways, which can be silenced by EZH2, have been shown to contribute to oncogenesis." (PMID 33163485, 2020). "Treg-selective deletion of essential Treg factors such as Neuropilin-1 (Nrp-1), suppressor of cytokine signaling 1 (SOCS1), enhancer of zeste homolog 2 (EZH2), Eos (IKzf4), or CARMA1 leads to Foxp3 downregulation and inflammatory cytokine secretion, conferring resistance to tumor growth in the host." (PMID 33024109, 2020). "However, the tumor volume and tumor increased with simultaneous interference with SNHG1 and overexpression of EZH2." (PMID 33194612, 2020). "EZH2, which is the catalytic subunit of the “polycomb repressive complex 2” (PRC2), is upregulated in SCLC cells upon the inactivation of the RB-E2F pathway, leading to a silencing of tumour suppressor genes and ultimately promoting SCLC cell proliferation." (PMID 33339368, 2020). "In primary malignant neoplasm of brain which including three DEGs (CDK4, EZH2, MYC)." (PMID 32696617, 2020). "Direct effects of EZH2 inhibition on the tumor itself are not likely to contribute to this phenotype as Rag knockout mice implanted with MB49 tumor cells and treated with an EZH2 inhibitor (CPI-1205) were observed to have equivalent survival and tumor growth kinetics as untreated controls." (PMID 33117406, 2020). "EZH2 is a core member of the PRC2 gene silencing complex that has methyltransferase activity and catalyses histone H3K27 trimethylation and heterochromatin formation, and thereby mediates tumour suppressor gene expression silencing." (PMID 32725802, 2020). "And our data showed that the tumor volume in nude mice treated with LINC00301 OE was markedly increased than that of in CTL group, while LINC00301 OE plus EZH2 KD significantly repressed tumor growth derived in nude mice when compared with LINC00301 OE group." (PMID 32878637, 2020). "The suppressive function of miR-138 was found to target enhancer of zeste homolog 2 (EZH2), pyruvate dehydrogenase kinase 1 and G protein-coupled receptor 124 (GPR124), SP1, SOX9, and cyclin D3 to inhibit tumor cell growth and migration." (PMID 32754587, 2020). "In our results chromosome 7, containing EZH2, showed a clonal gain in tumor tissue but not clonal gain in cell subpopulations." (PMID 32634135, 2020). "For instance, tumor cells can upregulate the ligands for ICPs such as PD-L1 and FGL-1, upregulate epigenetic silencing genes such as enhancer of zeste homolog 2 (EZH2), and/or secrete a large amount of soluble immune suppressive factors such as TGF-β and VEGF." (PMID 32370812, 2020). "The H3K27 histone N-methyltransferase EZH2 is a pusher of EMT leading to TKIs resistance, and its inhibitors may contribute to re-sensitize tumor to antiangiogenic treatment, which has been proven in preclinical test in RCC lines." (PMID 33510766, 2020). "Since DZNep is not a specific inhibitor only for EZH2, we tested (in mouse OM-derived tumor spheroids) other two inhibitors that more specifically repress EZH2 functions, Tazemetostat (EPZ-6438) and GSK-12652,53." (PMID 31996670, 2020). "Pearson and Spearman correlation tests revealed significant overall correlation between JMJD6 and EZH2 in both normal and tumor samples irrespective of the tumor histopathology (DCIS, IDC1 to IDC3) or molecular subtype (TNBC versus non-TNBC)." (PMID 33246425, 2020). "EZH2 aberration emerged in the all tumor samples, but not in the nontumor control; therefore, this was considered as a tumor-specific somatic gene variant." (PMID 33375764, 2020). "Therefore, our results showed that ZMYND8 regulates the poised epigenetic state of these tumor-promoting genes by modulating their respective epigenetic regulators, KDM5C and EZH2." (PMID 33323928, 2020). "Consequently, decreased amounts of H3k27me3 release the EZH2 silenced genes (such as HOXA9) and promote tumor progression." (PMID 32448308, 2020).
tumor (continued). "Enhancer of zeste homolog 2(EZH2), the catalytic subunit of the multiprotein histone methyltransferase complex known as polycomb repressive complex 2 (PRC2), plays an important role in tumorigenesis and tumor progression." (PMID 33718109, 2020). "For example, EZH2 has been found to act as both an oncogene and a tumor suppressor, since it maintains, rather than specifies, the transcriptional repression state of thousands of target genes." (PMID 32747629, 2020). "The results showed that 67.5% (81/120) of the tumor tissues exhibited significantly increased expression of EZH2 compared with paired adjacent non-tumor tissues." (PMID 32005028, 2020). "Although most studies suggest an oncogenic role of lncRNAs in the context of EZH2 and BTC, certain lncRNA species might also act as tumor suppressors." (PMID 32331331, 2020). "Further tumor promoting effects have been evidenced through the nuclear localization of STAT5, which has been demonstrated to recruit the histone methyltransferase EZH2 (enhancer of zeste homolog 2)." (PMID 31842362, 2019). "Even though EZH2 expression in the tumor center did not correlate with any of the clinical data, EZH2 expression at the tumor invasion front was significantly correlated with poor clinical outcome." (PMID 31317325, 2019). "We found that the tumor cell lines with high levels of HOTAIR and EZH2 were sensitive to AQB." (PMID 31367244, 2019). "In addition, suppression of EZH2 modulates the TME and enhances the infiltration of CD8+ and CD4+ effector T cells, which can favor tumor eradication." (PMID 31850055, 2019). "We observed that EZH2 induces enrichment of H3K27me3 at promoter loci of DAB2IP, a critical tumor suppressor, in a OCSC population, leading to enhanced survival of OCSCs and other malignant properties, including migration ability and chemoresistance (unpublished)." (PMID 31277278, 2019). "These inhibitors attenuated tumor growth, with AZD2014 exerting the most significant effects and also reduced mTORC1 activation (as assessed by EIF4EBP1 phosphorylation) and the expression of EZH2 and SUZ12 proteins." (PMID 31263101, 2019). "Furthermore, proliferation marker Ki67 IHC staining of these subcutaneous tumours displayed that enhanced expression of LINC01535 promoted HeLa cell proliferation in vivo, which was reversed by miR‐214 overexpression or EZH2 silencing." (PMID 31273925, 2019). "3-Deazaneplanocin A (DZNep) is an indirect EZH2 inhibitor, which not only prevents tri-methylation of H3K27, but also inhibits migration and proliferation, as well as induces cell death in many cancer cell lines and primary tumor cells." (PMID 31419226, 2019). "So far, there are also no studies considering a possible heterogeneity of EZH2 expression in the different tumor areas such as tumor center and invasion front." (PMID 31317325, 2019). "Second, there are no studies considering a possible heterogeneity of EZH2 expression in the center and at the invasion front of a tumor." (PMID 31317325, 2019). "On the other hand, overexpression of wt EZH2 has been also reported in B-NHL, with a positive correlation being observed between EZH2 transcript levels, tumor aggressiveness, and disease prognosis." (PMID 31681423, 2019). "However, a tumor xenograft study using 4 different cell lines of ARMS and EwS showed only limited anti-tumor activity of the EZH2 inhibitor tazemetostat for both entities." (PMID 31970591, 2019). "Next, we selected several EZH2 or LSD1 potential targets (P15, P21, KLF2, PTEN, TFPI2, LATS2, E-cadherin, and RND3) with tumor-suppressive role, and hypothesized that some of which may be associated with AGAP2-AS1-mediated carcinogenicity." (PMID 31186379, 2019). "AQB exhibited potent anti-tumor activity in the cells expressing high levels of HOTAIR and EZH2." (PMID 31367244, 2019). "But EZH2 expression and function in carcinogenesis and tumor progression of PTC has not yet been clarified." (PMID 31718595, 2019).
tumor (continued). "We have shown that the WNT10B/β-catenin/HMGA2/EZH2 signaling axis is critically important in chemo-resistant TNBC and that targeting this network can prolong survival by repressing primary tumor growth and multi-organ metastases to both the lungs and lymph nodes." (PMID 31861131, 2019). "By IHC in tumor nodules, NFATc2 shRNA transfectants lacked expression of NFATc2 and of EZH2, compared to control transfectants." (PMID 30710146, 2019). "High EZH2 protein expression by IHC correlated with smoking status (current and former smokers vs never smokers; P = 0.001) and larger tumor size (P = 0.04) in the MDACC dataset." (PMID 31456359, 2019). "Some evidences showed that EZH2 could silence KLF2 expression and inhibit the tumor-suppressor features of KLF2." (PMID 30266084, 2018). "Immunohistochemistry also showed that the protein expression levels of EZH2 and β-catenin were higher in tumor tissues than in adjacent non-tumor tissues." (PMID 29445149, 2018). "As the effects of Ezh2 inhibition in the tumors could be dependent on genes directly regulated by PRC2 and on secondary effects, we purified tumor cells at two time points to capture both types of data." (PMID 30487290, 2018). "Deletion of EZH2 in one patient-derived xenograft of G3 MB, Icb1572, never passaged in vitro, accelerated tumor progression, consistent with data in mouse G3 MBs (Bao-Han Vo and Martine F. Roussel, unpublished results)." (PMID 29178021, 2018). "The inhibition of the enhancer of zeste homolog 2 (EZH2), (a histone-lysine N-methyltransferase enzyme), and the reactivation of tumor suppressor miRNAs might lead to a functional cancer therapy regime strategy." (PMID 29596364, 2018). "As discovered by our findings, SNHG1is capable of binding to EZH2, which is a kind of histone methylation modification complex in the nucleus, thus suppressing the target gene’s expression, which includes CDKN1A, an innovative tumor suppressor in CCA." (PMID 29970899, 2018). "EZH2 is a H3K27 methyltransferase that has been recognized as a gene transcriptional regulator and a cancer driver, mainly through its ability to epigenetically and globally modify tumor-related genes." (PMID 30555330, 2018). "And there was a negative correlation between miR‐144‐3p expression and EZH2 expression in both adjacent tissues and tumor tissues." (PMID 30280514, 2018). "Since both BET and EZH2 inhibition result in increased H3K27me3 and decreased H3K27Ac, detection of these changes in H3 PTM over time may be useful for assessing tumor response to epigenetic therapies." (PMID 30647848, 2018). "In particular, enhancer of zeste homolog 2 (EZH2), the catalytic core subunit of PRC2, acts as an epigenetic silencer of many tumor suppressor genes through the trimethylation of lysine 27 on histone H3, an essential binding site for DNA methyl transferases and histone deacetylases." (PMID 30510924, 2018). "Inactivation of EZH2 in this context produced a synergistic effect with CTLA-4 and IL-2, suppressing tumor growth, which suggests that EZH2 expression may serve as an immune escape mechanism during immunotherapy." (PMID 30497521, 2018). "Consistent with the notion that Foxc1 was a target of transcriptional silencing by Ezh2, immunofluorescence revealed that Ezh2 and Foxc1 did not co-localize in endpoint Tet-ON PyVmT tumours." (PMID 29959321, 2018). "EZH2-mediated H3K27me3 and DNMT1-mediated DNA methylation repress the tumor production of T helper 1 (Th1)-type chemokines CXCL9 and CXCL10, and subsequently determine effector T-cell trafficking to the tumor microenvironment." (PMID 29556394, 2018). "Epigenetic silencing of the Th1-type chemokines CXCL9 and CXCL10 through mechanisms such as enhancer of zeste homolog 2 (EZH2)-mediated histone H3 lysine 27 trimethylation and DNA methyltransferase (DNMT) 1-mediated DNA methylation reduces effector T cell trafficking to the tumor microenvironment." (PMID 29403493, 2018).
tumor (continued). "Therefore, by decreasing EAF2 expression, EZH2 reduces VHL activity stabilizing HIF-1α expression, which is an effect that, in turn, increases tumor growth and metabolism favoring glycolysis." (PMID 30510924, 2018). "It is worth noting that in five of the nine E-MpMs, ELSs were also detected within the tumour nodules and, regardless of their intra- or peritumoural site, some had florid EZH2-labeled germinal centre (GC) B cells, thus indicating their active status." (PMID 30510965, 2018). "Next, we selected several EZH2, LSD1 or DNMT1 potential targets (P15, P21, LATS2, RND1, KLF2, NKD2, PTEN) with tumor-suppressor function and SPRY4, and hypothesized that they may involve in the contributions of SPRY4-IT1 to CCA progression." (PMID 29642935, 2018). "Moreover, among 152 patients with tumor stage T1, T2, and T3, the DFS rate in those displaying EZH2 gene upregulation was 39.8%, as compared with 55.6 % in those displaying EZH2 downregulation (log-rank test, p = 0.009)." (PMID 30469511, 2018). "Like the HMTs EZH2 and DOT1L, the HDM LSD1 is also correlated with tumor onset and progression, and some inhibitors of LSD1, including GSK2879552 and INCB059872, are under investigation in different phases of pre-clinical and clinical trials for application in the treatment of AML, MDS, and NSCLC." (PMID 30558227, 2018). "As seen in other neoplasias, Wang and colleagues also underscored an EZH2-mediated epigenetic activity of this lncRNA in MCL, since MALAT1 knock-down reduced EZH2 levels and decreased H3K27me3 at the promoter of the target genes p21WAF1 and p27KIP1, leading to cell cycle arrest at G1/S phase." (PMID 29739426, 2018). "miR-101 has been regarded as tumor-suppressive miRNA, and it could directly target 3’-UTR of EZH2 mRNA and inhibit proliferation, migration, and angiogenesis of tumor cells." (PMID 29445179, 2018). "Inhibition of EZH2 by ZLD1039 or miR-26a no longer induces tumour invading factors such as metalloprotease 2 and 9 (MMP2/9) and those related to epithelial-mesenchymal-transition (EMT) and, in contrast, induces differentiating factors." (PMID 29853899, 2018). "Furthermore, castration activates the CREB/EZH2 axis, concordantly affecting TSP1, angiogenesis and NE phenotypes in tumor xenografts." (PMID 30287808, 2018). "In tumors formed by the U87 cells without treatment a high expression of the EZH2 protein was found, and positively stained cells were distributed in all tumor." (PMID 28642877, 2017). "The EZH2-positive cell count in tumors formed by the nontreated U87 cells was 65 ± 13% of all tumor cells." (PMID 28642877, 2017). "In the nontreated U87 cell tumors, the EZH2 expression in cells has been very strongly expressed in tumor areas which invaded across the chorionic membrane to the mesenchyme and were surrounded by the thickened mesenchyme." (PMID 28642877, 2017). "The studied GBM U87 cell tumor samples showed a strong nuclear staining of EZH2 in U87 cell tumors without NaVP treatment, and a high expression of the EZH2 protein in the tumor cell nuclei was found." (PMID 28642877, 2017). "This indicates that the negative effects of the WF components on tumor cell drug resistance were more significant than the positive effects induced by inhibiting EZH2." (PMID 28968986, 2017). "Of note, the positive Ser21-phosphorylated EZH2 staining was not discriminative of tumor grade, stage, number of implants, tumor size or previous smoking history of the patients." (PMID 28060766, 2017). "Of note, the positive EZH2 staining was not discriminative of tumor grade, stage, number of implants, tumor size or previous smoking history of the patients." (PMID 28060766, 2017). "Interestingly, EZH2 inhibition had varying effects in a preclinical study of non-small cell lung cancers, with increased sensitization to topoisomerase II inhibitors in the tumor subset demonstrating BRG1/SMARCA4 loss-of-function mutations or EGFR gain-of-function mutations." (PMID 29093822, 2017).